ERBB2 (erb-b2 receptor tyrosine kinase 2)
Diseases named in the same sentence as ERBB2 in open-access papers (continued):
Sharing a sentence is not in itself a finding about the gene and the disease.
breast cancer (continued). "It was also verified that ERBB2 was associated with apoptosis and chemoresistance of breast cancer." (PMID 29163776, 2017). "Moreover, Par3 loss is associated with aberrant activation of proto-oncogene ErbB2, a key regulator of the invasion and metastasis of breast cancer." (PMID 28356139, 2017). "Moreover, despite multiple ErbB2-targeted therapeutics currently approved and in clinical trials, ErbB2+ breast cancers are associated with major clinical challenges due to the development of drug resistance." (PMID 28947975, 2017). "Examples of other TAAs that could be used in combination with ERBB2 in targeting breast cancer include melanoma-associated antigen-A4 (MAGE-A4), mesothelin, and MUC-1." (PMID 28885562, 2017). "Overexpression of the ERBB2 protein is associated with aggressive breast cancer subtypes." (PMID 28817097, 2017). "Breast cancer targeting using CAR technology has been well documented with studies reporting the generation of CAR for breast cancer-associated tumour antigens such as carbonic anhydrase IX, ERBB2, mesothelin, EGFR variant III (EGFRvIII), carcinoembryonic antigen (CEA), and Mucin-1 (MUC-1)." (PMID 28885562, 2017). "However, target deletion of PTEN leads to precocious development and neoplasia in the mammary gland using MMTV-Cre transgenic mice and there appeared breast cancer in ErbB2/Neu-overexpressing/PTEN-deficient mice." (PMID 28407687, 2017). "In this work, we set out to tackle the relevance of p140Cap in human breast cancer by analysing a large consecutive cohort of patients with invasive breast cancer and we demonstrated a strong association between p140Cap and improved survival of ERBB2 patients." (PMID 28300085, 2017). "Amin and colleagues have shown that PLPP1, a downstream ErbB2 signaling target, may be used as a diagnostic marker in breast cancer." (PMID 28851360, 2017). "In conclusion, p140Cap expression associates with reduced risk of metastasis (and death from cancer), in the ERBB2-amplified subgroup of breast cancer patients, arguing for a possible role of p140Cap in counteracting the migratory and/or metastatic ability of ERBB2-amplified tumour cells." (PMID 28300085, 2017). "Moreover, BRCA1-mutated breast cancers are frequently triple negative and by definition lack the expression of oestrogen receptor (ER), PR and amplification of the ERBB2 oncogene." (PMID 27881737, 2016). "Our study suggests that CDH1-altered ILC patients with ERBB2 mutations may represent an actionable group of patients who could benefit from targeted breast cancer therapy." (PMID 27811364, 2016). "In the present work, we have investigated the role of gal-7 in regulating mammary tumor development using gal-7-deficient mice (KOG7) and the mouse model of breast cancer FVB-Tg(MMTV-Erbb2)NK1Mul/J in which an activated form of Erbb2 is specifically expressed in mammary tissue." (PMID 27902734, 2016). "However, a few breast cancers with coexisting ERBB2 mutation and homogeneous or heterogeneous amplification have been already reported." (PMID 27602491, 2016). "Thus, the data suggest that nucleolin overexpression correlates with poor prognosis and increased risk of breast cancer in ErbB2-positive patients." (PMID 27542246, 2016). "In addition, ERBB4 overexpression was reported to be associated with favorable prognosis in breast cancer patients, especially in cases of ER-positive and/or ERBB2-amplified breast cancer." (PMID 26907936, 2016). "Indeed, ErbB2 amplification is a hallmark of human breast cancer, and a number of ErbB ligands are highly expressed in breast tumors, including the EGFR ligand TGFα and the ErbB3/ErbB4 ligand HRG." (PMID 27351228, 2016).
breast cancer (continued). "Mutation or overexpression of ErbB2 is regularly observed in lung and gastric cancers, but is more prevalent in breast cancer, where amplification and overexpression of the ErbB2 receptor is strongly linked with aggressiveness of the disease and a poor patient prognosis." (PMID 27597943, 2016). "The cardiotoxicity of antibodies has been associated to trastuzumab, a humanized anti-ErbB2 monoclonal antibody currently in clinical use for the therapy of breast carcinomas, which induces cardiac dysfunction when used in monotherapy, or in combination with anthracyclines." (PMID 26836985, 2016). "Interestingly enough, using the cBioportal, we found that the 9 ERBB2 mutated ILC cases of TCGA 2015 were CDH1 mutated with a significant correlation with a Fisher's exact test (p = 0.02) calculated among breast carcinomas of other histological subtypes." (PMID 27602491, 2016). "The Human HER2 oncogene, also known as neu/c-erbB2, is responsible for encoding a 185-kDa transmembrane receptor tyrosine kinase overexpressed in 20–30% of breast cancers and is associated with increased breast cancer recurrence and a worse prognosis." (PMID 26528430, 2015). "HER3 is thought to be an indispensible signaling substrate for HER2 (encoded by ERBB2) and is induced in breast cancer-brain metastases, though the molecular mechanisms by which this oncogenic dimer promotes the development of brain metastases are still elusive." (PMID 25668816, 2015). "On the basis of retrospective observations, risk factors for the development of CNS metastases from breast cancer included patient characteristics and biological features of tumors such as ER negativity, ErbB2 positivity, a large primary tumor and loss of histopathological differentiation." (PMID 26497551, 2015). "In breast cancer, overexpression and ERBB2 DNA amplification are generally closely linked." (PMID 25720673, 2015). "Studies over the last two decades have identified that amplified human epidermal growth factor receptor (HER‐2; c‐erbB‐2, neu) and its overexpression have been frequently implicated in the carcinogenesis and prognosis in a variety of solid tumours, especially breast cancer." (PMID 26305917, 2015). "Interestingly, a lot of rarely mutated putative driver genes that were detected in breast cancer have been described as copy number amplifications (e.g. ERBB2) or deletions (e.g. RB1, MEN1, PTEN) before." (PMID 25903787, 2015). "We then wondered whether different levels of some specific signaling molecules downstream of ERBB2 might influence susceptibility to and progression of breast cancer among mice." (PMID 25853295, 2015). "FASN has been linked to ErbB2-induced breast cancer chemoresistance to docetaxel." (PMID 26437434, 2015). "However, the overexpression of ErbB2 is clinically associated with approximately 30% of ovarian cancers, breast cancers, and has been shown to correlate with the metastasis, therapeutic resistance and poor prognosis of cancer." (PMID 25190023, 2014). "Both ErbB2 and TGFβ activation is associated to breast cancer stem cells/ tumor initiating cells." (PMID 24709902, 2014). "Notably, the use of the anti-cancer drug trastuzumab, an ERBB2 specific-inhibitor, causes cardiotoxicity and congestive heart failure in some breast cancer patients." (PMID 25269082, 2014). "Overexpression of HER2/Neu (encoded by the ERBB2 gene) is a common feature of human breast cancer." (PMID 24743474, 2014). "In addition to PAK1, the other PAK family members, PAK4, 5, and 6 are implicated in ErbB2-induced malignancy of breast cancer cells." (PMID 24709902, 2014). "Finally, we show that PGC-1α expression is positively correlated with that of the glutamine pathway in ERBB2+ breast cancer patients, and high expression of this pathway is associated with reduced patient survival." (PMID 24304688, 2013).
breast cancer (continued). "Moreover, high ShcA levels are enriched within the HER2 (ErbB2+) and basal (ER-/PR-/ErbB2-) subtypes and associate with poor outcome in breast cancer patients." (PMID 23408142, 2013). "Overexpression of ErbB2, which may activate the ErbB2/ErbB3 pathway, is often detected in breast cancer and associated with malignancy." (PMID 23308187, 2013). "Moreover, the potential involvement of HDAC1 in the ERBB2 promoter transcriptional repression is in agreement with previous studies associating HDAC1 expression with breast cancer progression and survival." (PMID 23421821, 2013). "To examine the consequences of LKB1 loss on mammary tumor formation driven specifically by the ErbB2 oncogene, we crossed mice containing a floxed LKB1 gene with a MMTV/NIC mouse model that expresses an activated form of ErbB2 (NDL2-5) and Cre recombinase from a single bicistronic transgene." (PMID 24280377, 2013). "The present study shows that in breast cancers the rs12976445 variant (in the T/C and C/C types as opposed to the T/T type) located in pri-hsa-miR-125a correlated with lower levels of hsa-miR-125a and that the mRNA levels of ERBB2 were increased." (PMID 23420759, 2013). "Moreover, the overexpression of FLOT2 in breast cancer is associated with the clinical stage, T and M classification, histological differentiation and ErbB-2 expression levels." (PMID 23945257, 2013). "Since mammary tumors from STK11−/−/NIC mice are positive for elevated ErbB2 expression, and 31% of HER2 positive breast cancers show loss of LKB1 expression, we investigated the effect of a next generation small molecule that targets the EGFR (ErbB1) and HER2, BIBW2992 (BIBW), on mTOR signaling." (PMID 23451056, 2013). "Our recent findings demonstrating that in the nucleus of breast cancer cells ErbB-2 is associated with Stat3 and PR, could help to explain the different sensitivity of both antibodies." (PMID 22356700, 2012). "Expression of these related genetic programs (SUMO-deficient PR and ERBB2 signaling) might represent independent means utilized by breast cancer cells to drive cell proliferation and survival." (PMID 22697792, 2012). "That suppression of CD44 is able to deplete heregulin-induced activation of erbB signalling and also depletes HA-promoted erbB2:erbB3 association suggest a potential value of therapeutically targeting CD44 in breast cancer, potentially to improve the effect of current targeted therapies." (PMID 23039365, 2012). "MIG-6 down-regulation in non-small cell lung cancer (NSCLC) is associated with increased EGFR signaling and poorly differentiated cancer, while loss of its expression in ErbB2-amplified breast carcinoma renders the cancer cells more resistant to Herceptin, the neutralizing antibody against ErbB2." (PMID 22701735, 2012). "ErbB2 is an oncogene associated with higher grades of breast carcinomas." (PMID 22567280, 2012). "Heterodimers between these two receptors have been shown to form the most potent mitogenic and transforming receptor complex in vitro, and coexpression of erbB2 and erbB3 have been shown to be significantly associated with decreased survival in breast cancer patients." (PMID 21939528, 2011). "How circulating IGF-I may promote breast cancer incidence is unknown, however, increased IGF-I signaling is linked to trastuzumab resistance in ErbB2 positive breast cancer." (PMID 21867536, 2011). "However, these mice were BRCA1-proficient and at risk for breast cancer because of overexpression of transgenic erbB2 (Her2), which is a member of the EGFR family and a direct target for the drugs used in those studies, that is, lapatinib or gefitinib." (PMID 21396117, 2011). "Amplification of ERBB2 oncogene and/or overexpression of HER2protein in breast cancer have been linked to poor prognosis and a differentialresponse to a variety of systemic treatments, therefore, HER2 status playsan important role in the prognosis and prediction for breast cancer patients." (PMID 21533253, 2011).
breast cancer (continued). "Syk has been shown to regulate Sp1 transcription factor activity in breast cancer cells; therefore, loss of syk may predispose breast epithelial cells to ErbB2-mediated downregulation of α2 integrin, resulting in a further step along the progression pathway." (PMID 22203845, 2011). "The assays may also be of use for selection of patients with ERBB2 positive breast cancer or non-small cell lung cancer carrying EGFR mutations." (PMID 20098682, 2010). "It is possible that a high diversity of breast cancer cell subtypes could be associated with active chromatin regions on 17q that are different from the ERBB2 amplicon region." (PMID 20158880, 2010). "In breast cancer, constitutive activity of NF-κB causes loss of estrogen receptor (ER) and resistance to chemo-, radiation-, and antibody-based therapies through signaling events downstream of ERBB2 or EGFR." (PMID 19399184, 2009). "This may explains at least in part why ERBB2 amplification is associated with a bona fide breast cancer subtype." (PMID 19226453, 2009). "ERBB2 is associated with stem cell biology in the mammary gland and breast cancer." (PMID 19226453, 2009). "The ERBB2 RTK is encoded by a gene that is amplified in about 20% breast cancers." (PMID 19226453, 2009). "Second, expression of either ErbB2 or ErbB3 is associated with poor prognosis in breast cancer." (PMID 18841159, 2008). "The effects of the olive oil-rich Mediterranean diet on breast cancer risk might be underestimated when HER2 (ERBB2) oncogene-positive and HER2-negative breast carcinomas are considered together." (PMID 19094209, 2008). "Understanding the precise level at which ErbB2 up-regulates survivin expression will help to delineate the underlying signal transduction pathways and will allow better targeting of survivin in ErbB2-overexpressing breast cancer cells." (PMID 18454859, 2008). "EGFR expression has also been linked to activation of ErbB2 in human breast cancers." (PMID 18320059, 2008). "TOP2A deletion is associated with poor prognosis in ERBB2-amplified breast carcinomas." (PMID 18702822, 2008). "Transfection of ErbB2 in MCF7 breast cancer cells that express ErbB3 caused a PI3K-dependent activation of Akt, and was associated with an increased resistance of the cells to multiple chemotherapeutic agents (paclitaxel, doxorubicin, 5-fluorouracil, etoposide, and camptothecin)." (PMID 19384426, 2007). "Nevertheless in an ErbB2 dependent mouse breast cancer model Muraoka and co-workers showed that while loss of one p27 allele accelerated breast cancer development loss of both alleles decreased cyclin D dependent kinase activity which correlated with an increased tumor latency." (PMID 17488529, 2007). "We aimed to determine whether common genetic variation (frequency >5%) in the ERBB2 amplicon is involved in breast cancer susceptibility." (PMID 17117180, 2006). "Interestingly, the estrogen receptor alpha and HER2/ERBB2, the major parameters characterizing 3 of the 5 different classes, are the goals for the most successful targeted therapies in breast cancer, underlining a fundamental role in biological control." (PMID 16536878, 2006). "Carriers of haplotype 2 in the CHEK2 gene seemed to have a decreased risk of death from breast cancer (P = 0.038) compared with haplotype 1 carriers, whereas carriers of the rare ERBB2 haplotypes seemed to have an increased risk of death from breast cancer (P = 0.009)." (PMID 17132159, 2006). "A gene thought to be involved in low-level susceptibility to breast cancer is ERBB2 (HER2)." (PMID 15743501, 2005). "Additionally, it was also observed that loss of PTEN activity is frequent in breast cancer and accompanied by increased activation of Akt, confirming that Akt can be activated by stimuli other than ErbB-2." (PMID 15987444, 2005).
breast cancer (continued). "Moreover, the overexpression of human epidermal growth factor receptor-2 (ErbB-2/HER-2), which is associated with poor survival in several human malignancies including breast cancers, is closely correlated with increased angiogenesis and expression of VEGF." (PMID 14710236, 2004). "Moreover, our recent documentation of differential survival outcomes in ErbB2-overexpressing breast cancers associated with different phosphorylation patterns supports the notion of multiple signalling pathways governing tumour growth phenotypes." (PMID 11953857, 2002). "Furthermore, identifying structural barriers and prescriber-specific factors associated with the overall likelihood of receiving ERBB2-targeted therapy in more recent time frames, even as guidelines broadly recommend use of these drugs, is crucial to improving quality of breast cancer care." (PMID 40310643, 2025). "The identification of ERBB2 mutations in 14% of patients, 2.1% of daughters, and 1.2% of sisters suggests a genetic basis for increased susceptibility in first-degree relatives, particularly in populations with high familial breast cancer prevalence, such as in Egypt." (PMID 41403731, 2025). "Trastuzumab Deruxtecan, an antibody-drug conjugate (ADC) consisting of a humanized anti-ERBB2 (HER2) monoclonal antibody linked to the topoisomerase I inhibitor Deruxtecan, represents a novel therapeutic option for patients with advanced hormone receptor-positive (HR+, e.g., ER+) breast cancer." (PMID 39991577, 2025). "In addition, whether the somatic mutational profile of primary breast cancer impacts the prognosis of patients with ER+/ERBB2‐ EBC remains unknown." (PMID 39031010, 2024). "Moreover, ERBB2 overexpression has been linked to increased breast cancer metastasis." (PMID 37859946, 2023). "drug category, as high ErbB2 expression in those cancer cell lines was found to be significantly associated with resistance to 40% of the drugs targeting protein stability and degradation, followed by breast cancer in which 30% of the drugs targeting Protein stab." (PMID 37508418, 2023). "Furthermore, given the known racial and ethnic disparities in breast cancer prognosis, it is important to describe the epidemiological characteristics of ERBB2-low breast cancer to understand the potential association with novel antibody-drug conjugates such as T-DXd on breast cancer disparities." (PMID 36821125, 2023). "ErbB2 can form homodimers or heterodimers with other ErbB family members to activate downstream signaling that enhances the survival and proliferation of oncogenic cells; therefore, overexpression of ErbB2 is associated with poor prognosis in patients with breast cancer." (PMID 35501821, 2022). "However, how loss of CHIP in ErbB2-overexpressing breast cancers might regulate ErbB2 itself is unclear." (PMID 34439093, 2021). "In breast cancer cells, previous studies showed that ErbB2 itself in shape of its p95 carboxy-terminal fragment or via an ErbB2-encoded miRNA downregulate ER expression; so in breast cancer, ErbB2 amplification is suspected to lead to endocrine therapy resistance." (PMID 32591879, 2021). "Thus, ErbB2 likely downregulates Irf6 levels in patients’ tumors, and Irf6 upregulation may be associated with trastuzumab sensitivity of breast cancer cells." (PMID 30545388, 2018). "Moreover, in vitro and in vivo data suggest that ERBB2-mutated breast cancer are sensitive to neratinib (irreversible anti-HER2 TKI) and that ERBB2-mutated colon cancers are more sensitive to dual HER2 inhibition (TKI + Mab) compared to monotherapy or reversible TKI." (PMID 29515767, 2018). "Given that we observed focal loss of PTEN in normal human breast tissue, our findings indicate that a percentage of patients with stromal loss of PTEN might be at risk for subsequent breast cancer via epithelial EGFR/ErbB2 activation and subsequent genomic instability." (PMID 30018330, 2018).